MMP9 (matrix metallopeptidase 9)
Diseases named in the same sentence as MMP9 in open-access papers (continued):
Sharing a sentence is not in itself a finding about the gene and the disease.
myocardial infarction (continued). "MMP2 was chosen not only for its similarity to MMP9 in terms of size and functionality, but also because MMP2 and MMP9 are closely related collagenases and involved in the turnover of the ECM after myocardial infarct." (PMID 36140171, 2022). "In patients presenting with acute myocardial infarction and major cardiovascular events (MACE) at the one-year follow-up, hs-CRP, I-CAM, and MMP-9 were significantly increased and MMP-9 was the most powerful predictor for MACE." (PMID 36362423, 2022). "Macrophage-specific overexpression of MMP-9 improved left ventricle function and decreased ECM synthesis by attenuating the inflammatory response after myocardial infarction." (PMID 34992607, 2021). "The inhibitors of MMP‐2 and MMP‐9, TIMP‐1 and TIMP‐2 are elevated in tissue and plasma during heart failure and myocardial infarction." (PMID 31932967, 2021). "MMPs were found in higher concentrations in atherosclerotic plaques, and patients with hypertension, myocardial infarction, and unstable angina had higher levels of circulating MMP2 and MMP9 than healthy people." (PMID 35050217, 2021). "MMP-2 and MMP-9 were studied for their roles in left ventricular remodeling and postmyocardial infarction prognosis since they are activated within the myocardial tissue after MI." (PMID 31205590, 2019). "Previously, serial samples of ACS patients after myocardial infarction revealed a dynamic quality in the circulating levels of MMP-8, MMP-9, and TIMP-1 in both the acute and the recovery period." (PMID 28278213, 2017). "Elevated expression and activity of MMP-13, MMP-9 and EMMPRIN are correlated with advanced atherosclerotic lesions followed by plaque rupture and myocardial infarction,which can be inhibited by curcumin." (PMID 25241044, 2014). "Meanwhile, recent studies showed that a variety of MMPs increase in the myocardium after myocardial infarction, including MMP-1, MMP-2, MMP-3, MMP-7, MMP-9, MMP-11, and so on." (PMID 25237357, 2014). "Intriguingly, our findings revealed that macrophage-specific MMP-9 overexpression exerts anti-inflammatory effects, consistent with reports showing that human MMP-9 overexpression in macrophages improves post-myocardial infarction cardiac function and attenuates age-related cardiac fibrosis in mice." (PMID 40244002, 2025). "MMP-9 codes for a matrix metalloproteinase induced during labour and MMP-9 is also increased in multiple cardiovascular diseases including hypertension and myocardial infarction." (PMID 38484284, 2024). "It was revealed that patients with plaque rupture and ACS (myocardial infarction versus unstable angina pectoris) had significantly higher levels of MMP-9 than patients who did not have plaque rupture." (PMID 35449607, 2022). "Our study advocates for the stratification of patients with acute myocardial infarction at risk of developing adverse events, based on the serum levels of two inflammatory biomarkers (I-CAM and MMP-9), regardless of presenting with STEMI or NSTEMI." (PMID 34362217, 2021). "MMP-9 was significantly elevated in patients with MACE (2255 ± 1226 vs. 1099 ± 706.1 ng/mL p = 0.0001) for the total number of subjects, and also during separate analyses according to the type of myocardial infarction." (PMID 34362217, 2021). "Taken together, our data show that beyond the current I(f), Ivabradine may induce cardiac protection against myocardial infarction by preventing the secretion of CyPA and binding to LG-EMMPRIN to prevent ECM-degrading MMP-9 expression in response to IR." (PMID 33809359, 2021). "Matrix metalloproteinase-9 (MMP9), a collagenase, is upregulated in the diabetic heart, and ablation of MMP9 decreases infarct size in the non-diabetic myocardial infarction heart." (PMID 32170070, 2020). "This study tested the hypothesis that MMP-9−/−tPA−/− double knock out (i.e., MTDKO) plays a crucial role in the prognostic outcome after acute myocardial infarction (AMI by ligation of left-coronary-artery) in MTDKO mouse." (PMID 32867392, 2020).
myocardial infarction (continued). "In rats with myocardial infarction, DHI treatment improved cardiac remodeling and preserves ventricular function by suppressing the expressions of TGF-β1 and fibrosis-related proteins (MMP-2 and MMP-9)." (PMID 33456666, 2020). "GBE could inhibit experimental rat myocardial remodeling after acute myocardial infarction via reduced transcription of TGF-β1, MMP-2 and MMP-9 genes and by the decreased expression of type I collagen, MMP-2 and MMP-9 proteins in myocardial cells." (PMID 26268459, 2015). "Low dose Omacor® (1 g/day) did not influence plasma IL-6 concentration in patients studied following myocardial infarction, while others reported a lack of effect of Omacor® on sCD40L and MMP-9 concentrations." (PMID 24065166, 2013). "For instance, the increase in MMP-9 level following the use of mobilizing agents such as SDF-1, VEGF and G-CSF or after a myocardial infarction, leads to an up-regulation of soluble kit, which ultimately results in an increase in MSC mobilization and proliferation." (PMID 18949088, 2007). "Importantly, MMP9 serum concentrations (but not MMP2) were previously shown to be increased in patients with cardiovascular disease due to acute myocardial infarction and MMP9 was proposed as a marker of inflammation in this disease." (PMID 37445827, 2023). "Ablation of MMP9 decreases infarct size in the non-diabetic myocardial infarction heart." (PMID 35886020, 2022). "One recent study reported that after the administration of NaHS, the area of myocardial fibrosis in myocardial infarction (MI) rats is reduced, and the level of type I collagen, type III collagen, and MMP-9 is reduced, and the heart function is improved." (PMID 34594474, 2021). "Over the past three decades, numerous studies have shown a strong connection between matrix metalloproteinase 9 (MMP-9) levels and myocardial infarction (MI) mortality and left ventricle remodeling and dysfunction." (PMID 33805901, 2021). "In addition, plasma MMP-9 levels are significantly increased in infarct-related arteries than in the femoral artery and peripheral vein and are positively correlated with the volume of myocardial infarction (MI) area, suggesting that MMP-9 may also be released from the infarcted myocardium." (PMID 33082709, 2020). "Various animal models of myocardial infarction (MI) showed an elevation of MMP2, and MMP9, as well as activation of their endogenous inhibitors, TIMPs -1,-2, and -4." (PMID 32271823, 2020). "At four weeks after MI, increases in MMP2 and MMP9 mRNA levels were observed in the Empty Bead group in both infarct and border regions of pig heart after myocardial infarction." (PMID 28003833, 2016). "Activation of a trans-valvular Impella CP pump, but not VA-ECMO, before reperfusion reduced myocardial infarct size and attenuated an increase in TNF-a and IL-6 levels and MMP-9 levels and activity in the LV and renal cortex." (PMID 33782857, 2022). "Our prior research indicated that while MMP-9 concentration may not predict acute myocardial infarction (MI) risk in the Ukrainian CAD population, carriers of the AG allele of the rs17576 single nucleotide variant (SNV) in the MMP-9 gene exhibited a reduced MI risk." (PMID 40224343, 2025).
periodontitis (190 papers, 2008 to 2026). An acute or chronic inflammatory process that affects the tissues that surround and support the teeth. "The study found that RT increased the levels of MMP-8 and MMP-9 and were linked to the clinical worsening of periodontitis." (PMID 40545647, 2025). "As previously reported, activity levels of the salivary biomarkers MMP-8, MMP-9, and IL-1β have been linked to periodontitis." (PMID 41002732, 2025). "MMPs, specifically collagenase (MMP-1) and gelatinase (MMP-9), have been implicated in the progression of periodontitis." (PMID 40007939, 2025). "Elevated levels of matrix metalloproteinase-9 (MMP-9) were observed in the vitamin-D-deficient group, suggesting a correlation between hypovitaminosis D and periodontitis severity." (PMID 41149095, 2025). "Overexpression and overactivation of MMPs result in periodontal tissue destruction, and profound MMP-8 and MMP-9 elevations are associated with periodontitis severity." (PMID 40332093, 2025). "After reviewing the seven studies on people of Indian origin and which met the inclusion criteria, evidence was found that periodontitis and MMP-9 (–1562C/T) are linked." (PMID 39553301, 2024). "MMP-9, which can cause pathological connective tissue destruction, is detected in higher amounts in chronic periodontitis." (PMID 39450334, 2024). "This systematic review included 1,046 participants in seven Indian studies, and substantial evidence was found for an association between MMP-9 (–1562C/T) and periodontitis in Indian population." (PMID 39553301, 2024). "The available literature suggests introducing salivary MMP-9 as an efficient biomarker for the diagnosis of periodontitis with a diagnostic ability > 80%." (PMID 39064296, 2024). "Our findings revealed elevated MMP8 and MMP9 in DS patients with periodontitis, indicating an increased risk for early development of destructive forms of periodontal disease in this population." (PMID 37448427, 2023). "MMP9 is one of the major collagen-degrading enzymes in saliva, which is associated with periodontitis and MMP-13 has also been found to be involved in periodontal tissue destruction and alveolar bone resorption." (PMID 37047877, 2023). "A previous study highlighted that MMP9 was associated with obesity and periodontitis and MMP-9 has been shown to be a more sensitive marker for periodontal inflammation." (PMID 37047877, 2023). "MMP-9 expression is associated with damage to periodontal tissue during the active stages of periodontitis." (PMID 36830029, 2023). "GCF levels of MMP-9 in early pregnancy are elevated in women with severe periodontitis and linked to the development of GDM." (PMID 37342498, 2023). "In this way, MMP-8 and MMP-9 are extremely valuable diagnostic tools in treating periodontitis, while MMP-13 affects the activity of osteoclasts and bone resorption, contributing to the destruction of the periodontal tissue." (PMID 37047877, 2023). "This signifies that type-II DM causes increased levels of MMP-9 to be released in its inflammation that are almost twice as much as the levels released in the inflammation caused by chronic periodontitis only." (PMID 35408573, 2022). "MMP9 was separately associated with both obesity and periodontitis in this study, but it was even more expressed in the saliva of pregnant women with the combination of these outcomes, as a result of those two distinct inflammatory processes." (PMID 36355174, 2022). "MMP-9 was used as model as it is found in high amounts in inflamed periodontitis sites and is strongly associated with the progression and severity of periodontitis." (PMID 35392377, 2022). "Preliminary evidence has shown that MMP-9 expression is associated with damage to periodontal tissue during the active stages of periodontitis." (PMID 35163727, 2022).
periodontitis (continued). "A possible explanation for the results of this study comes from other evidence showing that MMP-9-mediated immune response is associated with the presence of heat shock proteins released during periodontitis, exerting a specific action on T lymphocytes." (PMID 35163727, 2022). "Previous studies highlighted that MMP9 is one of the major collagen-degrading enzymes in saliva, which is associated with periodontitis." (PMID 36355174, 2022). "In this regard, some studies have shown that MMP-9 is increased in the gingival crevicular fluid during the initial phase of periodontitis, having a key role in the neoangiogenesis associated with the host response to periodontal pathogens." (PMID 35163727, 2022). "Both MMP-8 and MMP-9 are extremely valuable diagnostic tools in treating periodontitis, and future studies and healthcare policies should focus on implementing more accessible methods of chairside testing in order to reduce the prevalence of this disease." (PMID 35163727, 2022). "Preliminary evidence has demonstrated that the expression of MMP-9 is associated with periodontal tissue damage during active stages of periodontitis." (PMID 33810003, 2021). "In this regard, some reports have demonstrated upregulated MMP-9 in gingival crevicular fluid (GCF) during the initial phase of periodontitis, with a key role played by MMP-9 in neoangiogenesis associated with the host response to periodontal pathogens." (PMID 33810003, 2021). "In our meta-analysis, we accurately assessed the association between these MMP-2 -753C>T and MMP-9 -1562C>T polymorphisms and the risk of chronic/aggressive periodontitis by taking into account the effects of new published studies." (PMID 31497543, 2019). "The aim of this study was to investigate the influence of IL18, IL12, and MMP9 polymorphisms in the chronic periodontitis." (PMID 31065235, 2019). "With regard to periodontitis, a significant association between MMP-9, osteoactivin, IL-8, and macrophage inflammatory protein 1α and bacterial composition microbiota and cytokine profile in GCF has been identified in periodontal host homeostasis." (PMID 31281801, 2019). "MMP-3 (stromelysin) and MMP-9 (gelatinase B) have been strongly associated with the progression of periodontitis." (PMID 29321009, 2018). "Compared with the previous meta-analyses, we had a lager sample size than them, which increased the statistical power, and we found a reduced risk of MMP-9-1562 T allele with periodontitis susceptibility." (PMID 27095260, 2016). "Following full-text retrieval of the articles, two studies were eliminated as they investigated the association of the MMP-9 promoter −1562 C/T polymorphism with aggressive periodontitis." (PMID 27186490, 2016). "In the present meta-analysis, we aggregated data from published studies to estimate genetic associations between MMP gene, namely MMP-2-753 C/T, MMP-3-1171 A5/A6, MMP-8-799 C/T, and MMP-9-1562 C/T polymorphisms, and periodontitis susceptibility." (PMID 27095260, 2016). "Our results provided some evidence to support an elevated risk between periodontitis susceptibility and MMP-3-1171 A5 allele and MMP-8-799 T allele, and a reduced risk between periodontitis susceptibility and MMP-9-1562 T allele." (PMID 27095260, 2016). "Subgroup analyses suggested that the MMP-9-1562 C/T polymorphism reduced chronic periodontitis susceptibility and MMP-3-1171 A5/A6polymorphism increased chronic periodontitis susceptibility." (PMID 27095260, 2016). "Although many studies have focused on the association of the MMP-9 promoter −1562 C/T polymorphism with the susceptibility and/or severity of chronic periodontitis (CP), results have been inconsistent." (PMID 27186490, 2016). "The results based on 2,724 periodontitis patients and 3,438 controls showed that MMP-9-1562C/T, MMP-3-1171 A5/A6, and MMP-8-799C/T polymorphisms were associated with periodontitis susceptibility." (PMID 27095260, 2016).
periodontitis (continued). "We aimed to systematically investigate the potential association of matrix metalloproteinase (MMP)-9, -3, -2, and -8 gene polymorphisms with susceptibility to periodontitis using meta-analysis." (PMID 27095260, 2016). "BTC likely contributes to tissue destruction by inducing the production of inflammatory mediators such as matrix metalloproteinase‐9 (MMP‐9) and prostaglandin E2, which are implicated in the degradation of extracellular matrix and bone resorption in periodontitis." (PMID 40913361, 2026). "Additionally, it reduced the expression of MMP-9, which is linked to the tissue degradation associated with periodontitis." (PMID 40746873, 2025). "Among these biomarkers, MMP-8 and MMP-9 are proteins that cause tissue breakdown in periodontitis." (PMID 40545647, 2025). "Following the 24 months of treatment with the regimen, the regimen was found to directionally reduce bacterial amount and diversity while also statistically significantly reducing critical biomarkers (IL-1β, MMP-1, MMP-9) associated with inflammation and periodontitis." (PMID 41303313, 2025). "TIMPs, an MMP-9 inhibitor, may be biomarkers for diagnosing and monitoring periodontitis by reducing MMP activity linked to tissue destruction and disease progression." (PMID 39659491, 2024). "Based on the systemic anti-inflammatory effects of ω-3 PUFA supplementation, it could be assumed that there is a positive host modulation of inflammatory bone destruction and of the MMP-2 and MMP-9 activity caused by periodontitis." (PMID 37378834, 2024). "Our findings suggest that increased MMP8 and MMP9 in DS periodontitis patients could contribute to their heightened susceptibility to periodontal disease." (PMID 37448427, 2023). "MMP-9 was associated with periodontal tissue damage during active stages of periodontitis." (PMID 37365568, 2023). "However, MMP-2-753C > T and MMP-9-1562C > T polymorphisms had an influence on the susceptibility of periodontitis by ethnicity." (PMID 35454140, 2022). "In addition, polymorphisms in MMP-1, MMP-3, MMP-8, and MMP-9 are associated with chronic periodontitis susceptibility." (PMID 33477537, 2021). "In addition to the periodontitis group that was associated with increased MMP-9, patients who received both periodontal as well as orthodontic treatment displayed an augmentation in the inhibition of MMP-9 levels, compared with either treatment alone." (PMID 33498206, 2021). "In addition, gelatinases such as gelatinase A (MMP-2) and gelatinase B (MMP-9) have been associated with periodontitis." (PMID 34833990, 2021). "With respect to MMP-9, it is a gelatinase associated with the degradation of gelatin and type IV collagen and is identified in gingival crevicular fluid samples from patients with periodontitis." (PMID 33294463, 2020). "Methylation levels of the MMP-9 promoter were also associated with the duration of periodontitis." (PMID 32867386, 2020). "The results showed a significant association between MMP-9 -1562C>T polymorphism and periodontitis risk under recessive model (TT vs. TC+CC, OR=1.873, 95% CI=1.123–3.125, P=0.016), which suggests that the results of our meta-analysis are affected by HWE status." (PMID 31497543, 2019). "Therefore, to clarify precise associations of MMP-2-753 C>T and MMP-9-1562C>T polymorphisms with chronic (CP) and aggressive (AgP) periodontitis, we performed a systematic review and meta-analysis." (PMID 31497543, 2019). "Moreover, when stratifying the studies by HWE status, a significant association between MMP-9 -1562C>T polymorphism and periodontitis risk was observed only under recessive model (TT vs. TC+CC, OR=1.873, 95% CI=1.123–3.125, P=0.016)." (PMID 31497543, 2019). "MMP-9 is a gelatinase associated with degradation of gelatin and type IV collagen and is identified in samples of gingival crevicular fluid from patients with periodontitis." (PMID 31355267, 2019).